RLN1 (relaxin 1)
Description:
Relaxin is an ovarian hormone that acts with estrogen to produce dilatation of the birth canal in many mammals. May be involved in remodeling of connective tissues during pregnancy, promoting growth of pubic ligaments and ripening of the cervix.
Synonyms: H1; H1RLX; RLXH1; bA12D24.3.1; bA12D24.3.2
Tractability: Antibody: UniProt places it where antibodies can reach, with medium confidence; UniProt predicts a signal peptide or a membrane-spanning region; its Gene Ontology location is reachable by antibodies, with medium confidence. PROTAC: ubiquitination databases record sites on it.
Gene: Protein-coding gene on chromosome 9 (5,334,930 to 5,339,876, reverse strand). Ensembl gene ENSG00000107018.
Subcellular location: Secreted
Pathways (Reactome):
Cellular responses to stimuli: Attenuation phase; HSF1 activation; HSF1-dependent transactivation; Regulation of HSF1-mediated heat shock response
Gene Ontology:
Molecular function: protein binding; hormone activity
Biological process: female pregnancy; signal transduction
Cellular component: extracellular region
Genetic constraint (gnomAD): Loss-of-function variants: 3 observed, 4.44 expected, observed/expected ratio (o/e) 0.68, 90% interval 0.3 to 1.62. That is too few expected variants to judge how well the gene tolerates losing a copy. Missense variants: 274 observed, 211.31 expected, observed/expected ratio (o/e) 1.3, 90% interval 1.17 to 1.43. Synonymous variants: 100 observed, 85.24 expected, observed/expected ratio (o/e) 1.17, 90% interval 1 to 1.38.
Homologues: Orthologues: chimpanzee RLN1 (96% identical), rat Rln1 (49% identical), mouse Rln1 (48% identical), rabbit RLN1 (43% identical), dog RLN2 (39% identical). Paralogues in human: RLN2 (82% identical), INSL6 (25% identical), INSL4 (24% identical).
Diseases named in the same sentence as RLN1 in open-access papers:
RLN1 is named in the same sentence as 13 diseases in open-access papers, as found by Europe PMC text mining. Sharing a sentence is not in itself a finding about the gene and the disease. The quoted sentences say what the papers report.
liver fibrosis (2 papers, 2019 to 2026). "Collectively, these results indicated that human relaxin-2 can exert similar biological functions as murine relaxin-1 in mice to effectively alleviate liver fibrosis." (PMID 41552388, 2026).
Myocardial fibrosis (2 papers, 2019 to 2020). "The development of myocardial fibrosis also involves factors such as relaxin-1 (RLN1), growth hormone secretagogue receptor (GSHR), ADAMTS-1, and transient receptor potential melastatin 7 (TRPM7)." (PMID 33014530, 2020). "We found a moderate inverse correlation between RLN1 levels and degree of myocardial fibrosis in both ventricles (r = −0.357, p = 0.014 in the right ventricle vs. r = −0.321, p = 0.028 in the left ventricle with Masson’s trichrome staining)." (PMID 31231242, 2019). "Moreover, in our experiment, higher endogenous RLN1 levels were accompanied by significantly lower amount of myocardial fibrosis in patients with HFrEF." (PMID 31231242, 2019).
prostate carcinoma (2 papers, 2012 to 2019). A carcinoma that arises from epithelial cells of the prostate gland. "RLN1 is known to form a fusion with RLN2 in LNCaP cells as well as in normal and prostate cancer tissues." (PMID 31303963, 2019). "Relaxin 1 is a candidate protein that was not identified in any of the proteomes but its expression was confirmed by semi-quantitative RT-PCR in prostate carcinomas." (PMID 22515324, 2012).
Sciatica (2 papers, 2021 to 2022). Pain in the lower back and hip radiating in the distribution of the sciatic nerve. "To facilitate the diagnosis of sciatica by clinicians using the selected DEIRGs (RLN1, EREG, FAM19A4, WFIKKN1, and CRP), we constructed a nomogram model." (PMID 34925462, 2021). "AZU1, BPI, TCF7L2, and WFIKKN1 were upregulated in sciatica patients, while ANGPTL4, CRP, EREG, FAM19A4, FGF1, LOC100129216, PLXNB1, RLN1, and RXFP2 were downregulated." (PMID 34925462, 2021).
fibrosis (1 paper, 2026). the formation of excess fibrous connective tissue in an organ or tissue in a reparative or reactive process. "The human genome contains three relaxin genes, among which relaxin-2 (RLN2) shares similar antifibrosis effects with mouse relaxin-1 (RLN1) in murine fibrosis models, allowing early-stage development of human relaxin-based drugs to be tested in mouse models." (PMID 41552388, 2026).
heart failure (1 paper, 2019). Inability of the heart to pump blood at an adequate rate to meet tissue metabolic requirements. "Here, we aimed to assess endogenous, circulating RLN1 levels in patients with heart failure with reduced ejection fraction (HFrEF) of ischemic origin." (PMID 31231242, 2019).
pulmonary fibrosis (1 paper, 2019). Chronic progressive interstitial lung disorder characterized by the replacement of the lung tissue by connective tissue, leading to progressive dyspnea, respiratory failure, or right heart failure. "Thorough clinical study should answer how diastolic and systolic PAP changes, mirroring RLN1 levels and the degree of pulmonary fibrosis." (PMID 31231242, 2019).
pulmonary hypertension (1 paper, 2019). Increased pressure within the pulmonary circulation due to lung or heart disorder. "Our study was limited to histology samples from human hearts and not lungs, but further investigations may reveal that RLN1 could be a therapeutic target in defined forms of pulmonary hypertension." (PMID 31231242, 2019).
tumor (2 papers, 2014 to 2025). "Supposedly, local relaxin levels were rather high in this model, RLN1 mRNA expression being described as more than fivefold increased in the monocyte approach and 50–180 fold in the transfected tumour cells." (PMID 23963762, 2014). "In tumor models, gene delivery of RLN-1 promoted the infiltration of cytotoxic and antigen-presenting immune cells (CD8+ T cells, dendritic cells, NK cells) and simultaneously reduced Tregs, effectively shifting the tumor microenvironment toward an anti-tumor, immunostimulatory phenotype." (PMID 41196672, 2025).
cancer (1 paper, 2013). A tumor composed of atypical neoplastic, often pleomorphic cells that invade other tissues. "Considering the closest flanking genes of intergenic SNPs, the following are noteworthy and could contribute to the carcinogenic process, as has been reported for other cancer types: PRDM1, ATG5, MYC, EID, RLN1, CD274." (PMID 23626673, 2013).
RLN1 also shares sentences with these, for which no sentence is quoted: coronary artery disease (1 paper); COVID-19 (1); nonalcoholic steatohepatitis (1).